ABCG2 (ATP binding cassette subfamily G member 2 (JR blood group))
Diseases named in the same sentence as ABCG2 in open-access papers (continued):
Sharing a sentence is not in itself a finding about the gene and the disease.
leukemia (continued). "The physiological consequence of ABCG2 multidrug transport activity in leukaemia, and some solid tumours is the acquisition of cancer multidrug resistance." (PMID 21991363, 2011). "ABCG2 is expressed in leukemia, germ cell cancers, as well as cancers of the breast, prostate, and lung." (PMID 17615543, 2007). "The other genes affected by MPs in cancer cells are ABCB1 and ABCG2 in Leukemia." (PMID 41378310, 2025). "ABCG2 functions as an efflux transporter that can extrude a wide variety of chemotherapy drugs out of the cells, thereby reducing their effectiveness and contributing to drug resistance in leukemia cells." (PMID 41378310, 2025). "Finally, Wnt and Hedgehog pathways, involved in the maintenance of leukemia stem cell survival, bind the ABCG2 promoter and increase protein expression." (PMID 38255216, 2024). "It is possible that the acquisition by ABCG2-overexpressing leukemic cells of stem-cell-like properties eventually favors their survival in transplant preparative regimens and their escape from post-transplant graft versus the leukemia effect." (PMID 37108308, 2023). "We also demonstrated that overexpression of MMP9 and ABCG2 in the leukemia cell line could induce apoptosis and differentiation, indicating that these two genes could be potential targets for AML therapy." (PMID 34093860, 2021). "By decreasing ABCG2 expression, cancer stem cell subpopulations could be eliminated in patient-derived leukemia cells." (PMID 33066132, 2020). "ABCG2 is also known as a stem cell marker in immature myeloid and leukaemia stem cells." (PMID 28880238, 2017). "Moreover, CSCs are also responsible for the drug resistance of the cancer cells by expressing multidrug resistance proteins, for example, different ATP-binding cassette (ABC) transporters, e.g., MRP1 (ABCC1) and (ABCG2), which prevent damage from drugs and therapies in cancers like leukemia." (PMID 38891090, 2024). "Moreover, a higher expression in leukemic cells with more immature immunophenotypes (CD34+/CD38- and CD34+/CD33-) was observed, and the same subgroups also showed a reduced mitoxantrone retention compared to more mature leukemia cells, confirming the efflux activity of ABCG2." (PMID 37108308, 2023). "In the same study, they reported that ensartinib at 10 μM could reverse P-gp-mediated resistance to daunorubicin and ABCG2-mediated resistance to mitoxantrone in MDCKII cells transduced with P-gp or ABCG2, and in the human leukemia HL60 cell line overexpressing P-gp or ABCG2." (PMID 35565470, 2022). "Moreover, Apatinib could reverse ABCB1- and ABCG2-mediated multidrug resistance in solid tumors as well as in leukemia cell lines, thereby enhancing the efficacy of chemotherapeutic agents." (PMID 29490645, 2018). "However, it must be underlined that in vitro tests were performed in systems with very high ABCG2 expression and that, in wild leukemia samples, ABCG2 levels are significantly lower than in cell lines, and ABCG2 inhibition may be reached with lower concentrations." (PMID 38255216, 2024). "In the leukemia setting, high expression of c-MYC-driven ABCG2 was observed in CD34 cells of chronic myeloid leukemia." (PMID 38255216, 2024). "In vitro studies in leukemia cell lines K562 and K562/A02 transiently transfected with miR-98 show that miR-98 upregulation results in reduced E2F1 levels, a reduction of ABCG2 levels, and increased chemosensitivity." (PMID 38255216, 2024). "To do this, we used leukemia K562 cells with high and moderate expressions of ABCB1, K562/DoxDR3 and K562/DoxDR2, and ABCG2, K562/ABCG2CL10 and K562/ABCG2CL4, respectively." (PMID 33573093, 2021). "The frequent ABCG2 and ABCB1 co-expression on leukemia cells, with synergistic effects on drug efflux, may have a role in reducing the complete remission rate and in favoring early relapse." (PMID 38255216, 2024). "In some cancers, e.g., leukemia, ABCB1 and ABCG2 are commonly co-expressed." (PMID 33066132, 2020).
leukemia (continued). "Furthermore, 14C-AZA IUR in ABCG2-overexpressing leukemia cells (K562-ABCG2B) did not alter with ABCG2 inhibitor KO143 (12.14 ± 1.01 ng vs. 12.24 ± 1.09 ng, p = 0.922)." (PMID 36834962, 2023).
colorectal cancer (87 papers, 2008 to 2026). A primary or metastatic malignant neoplasm that affects the colon or rectum. "As our present findings, and some previous studies, found ABCG2 gene and/or protein expression to be associated with colorectal cancer clinical parameters, the present study also attempted to translate these associations into patient survival." (PMID 37445716, 2023). "The frequent deregulation of ABCG2 expression in various cancers prompted our search for the molecular mechanisms underlying the decrease in ABCG2 expression in colorectal cancer, namely the sequence changes and methylation of the ABCG2 gene." (PMID 37445716, 2023). "It is still not fully understood if the downregulation of ABCG2 expression in colorectal cancer is a cause or a consequence of carcinogenesis." (PMID 37445716, 2023). "In total, ABCG2 alterations were detected in 1.5% of colorectal cancer patients profiled for mutation, copy number changes and structural variants." (PMID 37445716, 2023). "As ABCG2 was found to be commonly underexpressed in colorectal carcinomas, the mutational and methylation status of the gene was analysed." (PMID 37445716, 2023). "Therefore, the detection of ABCG2 can not only identify a possible risk of colorectal cancer risk but also support survival prediction and treatment strategies." (PMID 28229027, 2017). "Therefore, the development of new ABCG2 inhibitors that block the active causes of MDR may provide a strategy for the treatment of colorectal cancer." (PMID 38855753, 2024). "Additionally, we found that ataxia-telangiectasia mutated (ATM) kinase inhibitor AZ32 could sensitize ABCG2-overexpressing colorectal cancer cells to ABCG2 substrate chemotherapeutic drugs mitoxantrone and doxorubicin by retaining them inside cells." (PMID 34094985, 2021). "According to the mRNA expression levels of ABCB1, ABCC1, and ABCG2 transporters in colorectal cancer patients, there is a significant difference in the expression levels of these ABC transporters." (PMID 41557172, 2026). "SCO-101 has previously been studied together with chemotherapy in patients with colorectal cancer, where the compound counteracts resistance to irinotecan by inhibiting the drug efflux pump ABCG2 and the metabolic liver enzyme UGT1A1." (PMID 40272619, 2025). "For instance, fisetin controls miR-3664-3p expression in HCT116 cells, thereby decreasing drug resistance of colorectal cancer cells by targeting ABCG2, CYP3A4, MCL1, and MLH1." (PMID 41470858, 2025). "β-sitosterol, an active ingredient of PPA, inhibits BCRP/ABCG2 to reverse the drug-resistance of drug-resistant colorectal cancer cells to oxaliplatin." (PMID 38324023, 2024). "We observed that the synergy for the gefitinib/SN-38 combination in SLFN11 positive colorectal cancer cells is correlated with the ABCG2 expression." (PMID 39033209, 2024). "According to the available literature, some authors have shown cellular irinotecan resistance in colorectal cancer cells due to an increase in a drug efflux transporter called ABCG2." (PMID 36829677, 2023). "In the present study, the data provided by the cBioPortal indicated that ABCG2 sequence changes are rare events in colorectal cancer." (PMID 37445716, 2023). "In contrast, the transmembrane transporter ABCG2 induces mitochondrial efflux of PpIX and is expressed, e.g., in malignant gliomas, breast and colorectal cancer." (PMID 36612300, 2023). "Spheroid culture from the HT-29 cell line, a more realistic colorectal cancer in vitro model, shows significantly higher expression of ABCG2, NANOG, SOX2 and POU5F1 compared to 2D cell culture conditions." (PMID 37445716, 2023). "Lastly, Kaplan–Meier curves were prepared to evaluate the influence of ABCG2 protein and gene expression on the survival time of colorectal cancer patients." (PMID 37445716, 2023).
colorectal cancer (continued). "Assuming 10% positive staining as a minimal cutoff for positivity in our wet analysis, our present findings confirm ABCG2 protein expression in three-quarters of colorectal cancer patients." (PMID 37445716, 2023). "Changes in gene methylation occur frequently during cancerogenesis, thus influencing the expression of the genes important for transformation, the methylation level of the ABCG2 gene was inspected in colorectal cancer." (PMID 37445716, 2023). "In conclusion, GSK2606414 can sensitize ABCG2-overexpressed multidrug-resistant colorectal cancer cells to chemotherapy drugs and can be used as a potential inhibitor of ABCG2." (PMID 38002103, 2023). "As the main drug resistance marker, ABCG2 is also critical for colorectal cancer (CRC) evolution, in particular cancer stem–like traits expansion." (PMID 37708089, 2023). "These interactions require further in-depth research to reveal the significance of ABCG2 and its protein expression in colorectal cancer." (PMID 37445716, 2023). "The findings from the in silico analysis and wet experiments indicate that ABCG2 gene expression is commonly deregulated in cancerogenesis, and a decrease in the expression of the gene is a general feature of colorectal cancer cells." (PMID 37445716, 2023). "Sorafenib can be used to treat colorectal cancers resistant to irinotecan-based chemotherapy by inhibiting the ABCG2 drug efflux pump." (PMID 35872794, 2022). "ABCG2 has been further shown to contribute to cisplatin resistance in ALDHA1 colorectal cancer stem cells and can be regulated by miR-199a/b." (PMID 35836256, 2022). "In this study, we established an ABCG2-knockout human colorectal cancer cell line by CRISPR-Cas9 mediated genome editing technology which we have used previously." (PMID 34094985, 2021). "Prior reports have suggested the importance of miRNAs in DDP resistance; for example, miR-199a elevates the expression of ABCG2 and thereby augments the resistance of colorectal cancer stem cells to DDP." (PMID 34876558, 2021). "Gedatolisib competitively increased the accumulation of tritium-labeled substrate-drugs in both ABCB1- and ABCG2-overexpression colorectal cancer cells." (PMID 33593355, 2021). "In present study, we evaluated the role of ABCB1 and ABCG2 in process of gedatolisib resistance in colorectal cancer cells." (PMID 33593355, 2021). "In this study, an ABCG2-knockout colorectal cancer cell line was established to assist inhibitor screening." (PMID 34094985, 2021). "To investigate the effect of AZ32 on ABCG2-mediated MDR in colorectal cancer cells, we firstly examined the cytotoxicity of AZ32 in the ABCG2-overexpressing MDR colorectal cancer cells S1-M1-80 and its parental S1 cells." (PMID 34094985, 2021). "ABCG2 gene amplification has been reported for a variety of cancer types, e.g., breast and colorectal cancer, and glioblastoma." (PMID 33066132, 2020). "Analyzing PrognoScan database indicated that elevated expression of ABCG1 and ABCG2 were correlated with poor prognosis of patients suffering from colorectal cancer and head and neck squamous cell carcinoma." (PMID 30364132, 2018). "The ATP-binding cassette transporters ABCG2 and ABCB1 have previously been associated with chemotherapy resistance, early disease recurrence and shorter survival in colorectal cancer." (PMID 28877221, 2017). "Reportedly, CD133+ colorectal cancer cells had chemoresistance to 5-FU via survivin and ABCG2 expression, and ABCG2 knockdown inhibited the self-renewal capacity of these cells, and enhanced chemotherapy-induced apoptosis." (PMID 28938696, 2017). "Contradictory results have been reported for immunohistochemical studies of ABCG2 protein expression in colorectal cancer (CRC), probably because of the use of different antibodies and scoring approaches." (PMID 27257141, 2016).
colorectal cancer (continued). "One study showed that exposure of the human colorectal cancer cell line HCT116 to SN-38 induces the expression of ABCG2 protein, and overexpression of ABCG2 suggests high levels of resistance to SN-38." (PMID 26966430, 2016). "It was also reported that miR-328 can decrease the chemoresistance of glioblastoma (GBM) and colorectal cancer (CRC) stem cells by downregulating ATP-binding cassette sub-family G member 2 (ABCG2) protein levels." (PMID 25605016, 2015). "Another study identified miR-328 in the SP of colorectal cancer cells and demonstrated that expression of miR-328 correlated with high a SP fraction, and that the main targets of miR-328 were the ABCG2 transporter and the MMP16 gene." (PMID 24386225, 2013). "Additionally, increased ABCG2 expression has also been identified in irinotecan-resistant colorectal cancer (CRC) cell lines and metastatic patients undergoing treatment with irinotecan." (PMID 39931465, 2025). "To understand whether this correlation is also valid in other cancers, we investigated the correlation between the CI of EGFR inhibitor/SN-38 combination with ABCG2 expression in colorectal cancer cells using data reported in the literature." (PMID 39033209, 2024). "It has reported that natural product extract might suppress ABCG2-mediated MDR in colorectal cancer through inhibiting NF-kB signaling pathway." (PMID 38576495, 2024). "In this study, we find that dorsomorphin (also known as compound C or BML-275) potently inhibits the transporter activity of ABCG2, thereby preserving the chemotherapeutic agents mitoxantrone and doxorubicin to antagonize MDR in ABCG2-overexpressing colorectal cancer cells." (PMID 38855753, 2024). "Some studies have suggested that the ABCG2 gene and its protein may act as indicators for the prediction of irinotecan-based therapy outcomes in colorectal cancer patients." (PMID 37445716, 2023). "As the ABCG2 mRNA expression was found to be substantially decreased in colorectal cancer, the expression and localization of ABCG2 protein in colorectal cancer and corresponding normal tissues was determined based on the immunohistochemistry staining images collected in the Human Protein Atlas." (PMID 37445716, 2023). "Moreover, low miR-203 expression in colorectal cancer leads to ABCG2 promoter methylation and significantly reduced expression by attenuating the inhibition of DNMT3B, which was consistent with our results." (PMID 37421455, 2023). "Furthermore, to validate findings from the in silico analysis, ABCG2 gene and protein expression was measured in a cohort of colorectal cancer patients to determine their prognostic significance." (PMID 37445716, 2023). "Importantly, some studies indicate that ABCG2 sequence variants may be involved in modulating colorectal cancer risk, as the expression and activity of the transporter in the bowels can differ between individuals, due at least in part to genetic polymorphisms of the ABCG2 gene." (PMID 37445716, 2023). "Unfortunately, our validation analysis in colorectal cancer patient cohort did not identify any significant association between ABCG2 expression, at the mRNA or protein level, and clinicopathological parameters." (PMID 37445716, 2023). "A substantial decrease in ABCG2 mRNA and protein expression was observed in colorectal cancer, suggesting that it may play an important role in the carcinogenesis process and influence cancer progression." (PMID 37445716, 2023). "Therefore, our data indicate that the upregulation of miR-199a/b in ALDHA1 colorectal cancer stem cells leads to cisplatin resistance through Wnt/β-catenin-ABCG2 signaling." (PMID 35836256, 2022). "All these data suggest that AZ32 could inhibit the transporter activity of ABCG2 to reverse ABCG2-mediated multidrug resistance in colorectal cancer by competing with the substrate chemotherapeutic drugs to bind ABCG2." (PMID 34094985, 2021).
colorectal cancer (continued). "However, the combined effect of AZ32 with ABCG2-substrate chemotherapeutic drugs in colorectal cancer need to be further validated in vivo." (PMID 34094985, 2021). "In colorectal cancers, upregulation of miR-199a/b has been reported to responsible for cisplatin resistance via Wnt/β-catenin-ABCG2 axis, indicated that there are a series of potential pathways which could mediate ABC transporter expression in cancers." (PMID 33593355, 2021). "In conclusion, our result demonstrated that AZ32 could potently reverse ABCG2-mediated MDR in colorectal cancer." (PMID 34094985, 2021). "This means that co-administration of gedatolisib with ABCB1 or ABCG2 inhibitors may have potential benefits to avoid gedatolisib resistance and improve the efficacy of gedatolisib in colorectal cancer." (PMID 33593355, 2021). "Further results showed that AZ32 could enhance the intracellular accumulation of mitoxantrone, doxorubicin, and rhodamine 123 in ABCG2-overexpressing colorectal cancer cells." (PMID 34094985, 2021). "In addition, as our immunofluorescence results illustrated, gedatolisib did not significantly altered the subcellular localization of ABCB1 or ABCG2 in drug-resistant colorectal cancer cells." (PMID 33593355, 2021). "Moreover, gedatolisib significantly increased the protein expression level of ABCB1 and ABCG2 in colorectal cancer cells." (PMID 33593355, 2021). "As ABCG2 has previously been shown to be critical for ALA-PDT in different human cancers, including brain and colorectal cancers, inhibition of ABCG2 could potentially enhance the efficacy of ALA-PDT in treatment of HNC." (PMID 32957726, 2020). "Similarly, overexpression of miRNA-3163 has been found to decrease ABCG2 expression in retinoblastoma stem cells, leading to increased sensitivity to cisplatin.Another study found that miR-548c-3p can reduce ABCG2 expression, making colorectal cancer cells more responsive to 5-fluorouracil." (PMID 39931465, 2025). "In this study, we found that ataxia-telangiectasia mutated (ATM) kinase inhibitor AZ32 was a potent inhibitor of ABCG2 and could sensitize ABCG2-overexpressing colorectal cancer cells to chemotherapeutic drugs mitoxantrone and doxorubicin by increasing their intracellular concentrations." (PMID 34094985, 2021). "To examine whether AZ32 reversed ABCG2-mediated MDR in colorectal cancer cells is due to inhibition of the transporter activity of ABCG2, we detected the intracellular levels of three ABCG2 substrates mitoxantrone, doxorubicin and rhodamine 123 in the presence or absence of AZ32." (PMID 34094985, 2021). "In conclusion, targeting CK1α might be a robust approach to increase sensitivity of colorectal cancer cells to 5-FU through Wnt signaling pathway, G2 and S phase arrests as well as G1 arrest, depletion of the mRNA levels of ABCG2, and autophagy flux inhibition." (PMID 34536148, 2021). "Hence, in present study, we focused on the effects of ABCB1 and ABCG2-mediated gedatolisib resistance in colorectal cancer cells, which may challenge its clinical administration effect." (PMID 33593355, 2021). "In conclusion, our result demonstrated that AZ32 could potently reverse ABCG2-mediated MDR in colorectal cancer by inhibit the transporter activity of ABCG2, which is supported by the predicted binding mode that presented the hydrophobic interactions of AZ32 within the drug binding cavity of ABCG2." (PMID 34094985, 2021). "Therefore, the combination of AZ32 with ABCG2-substrate chemotherapeutic drugs may be a potential strategy to overcome MDR in colorectal cancer." (PMID 34094985, 2021). "The higher expression of ABCG2 and ALDH1 in HCT-116 cells suggests a potential role in drug resistance and stem-like properties specific to colorectal cancer." (PMID 38787133, 2024). "OX@Se-MnP NPs reversed MDR in colorectal cancer by down-regulating the expression of MDR-related ABC (ATP binding cassette) transporters proteins (e.g., ABCB1, ABCC1 and ABCG2)." (PMID 36859296, 2023).